TPPP2 (tubulin polymerization promoting protein family member 2)
Description:
Probable regulator of microtubule dynamics required for sperm motility (Probable). In contrast to other members of the family, has no microtubule bundling activity.
Synonyms: C14orf8; p25beta; p18; CT152; TPPP/p18
Tractability: No criterion of Open Targets' tractability assessment is met for any kind of drug.
Gene: Protein-coding gene on chromosome 14 (21,024,109 to 21,036,276, forward strand). Ensembl gene ENSG00000179636.
Subcellular location: Cytoplasm, cytosol; Cell projection, cilium, flagellum
Subcellular location (Human Protein Atlas): Connecting piece; Mid piece; Principal piece
Gene Ontology:
Molecular function: tubulin binding
Biological process: microtubule bundle formation; regulation of flagellated sperm motility; microtubule polymerization; positive regulation of protein polymerization
Cellular component: cytosol; microtubule; sperm flagellum; motile cilium
Genetic constraint (gnomAD): Loss-of-function variants: 8 observed, 13.82 expected, observed/expected ratio (o/e) 0.58, 90% interval 0.34 to 1.04. The upper end of that interval is the gene's LOEUF score, 1.04, which puts it in group 4 of 6, group 1 being the genes least tolerant of losing a copy. Missense variants: 213 observed, 227 expected, observed/expected ratio (o/e) 0.94, 90% interval 0.84 to 1.05. Synonymous variants: 81 observed, 84.98 expected, observed/expected ratio (o/e) 0.95, 90% interval 0.8 to 1.15.
Homologues: Orthologues: macaque TPPP2 (97% identical), chimpanzee TPPP2 (96% identical), pig TPPP2 (90% identical), rabbit TPPP2 (89% identical), dog TPPP2 (88% identical), mouse Tppp2 (84% identical), guinea pig TPPP2 (82% identical), zebrafish tppp2 (62% identical), Caenorhabditis elegans tppp-1 (38% identical), Drosophila melanogaster ringer (36% identical). Paralogues in human: TPPP3 (63% identical), TPPP (58% identical).
Diseases named in the same sentence as TPPP2 in open-access papers:
TPPP2 is named in the same sentence as 4 diseases in open-access papers, as found by Europe PMC text mining. Sharing a sentence is not in itself a finding about the gene and the disease. The quoted sentences say what the papers report.
male infertility (3 papers, 2019 to 2021). The inability of the male to effect fertilization of an ovum after a specified period of unprotected intercourse. "TPPP2 is likely to be a potential pathogenic factor in male infertility." (PMID 30680919, 2019). "In line with this, an association between mitochondrial dysfunctionality and male infertility as a result of a diminished sperm motility has been reported for several knockout models (VPS13A, Tppp2, Gykl1, and Gk2)." (PMID 34765607, 2021).
breast carcinoma (1 paper, 2023). "No variants were significantly associated with breast cancer risk in UKBiobank after correction for multiple testing, but variants in BICD2 (p = 0.03) and TPPP2 (p = 0.02, OR = 1.95) were independently significant." (PMID 38136396, 2023).
testicular cancer (1 paper, 2025). A primary or metastatic malignant neoplasm that affects the testis. "TPPP2 was found via proteomic analysis to be involved in testicular cancer." (PMID 40358182, 2025).
TPPP2 also shares sentences with these, for which no sentence is quoted: Azoospermia (1 paper).